IFNG (interferon gamma)
Diseases named in the same sentence as IFNG in open-access papers (continued):
Sharing a sentence is not in itself a finding about the gene and the disease.
tumor (continued). "Additionally, we performed GO analysis, demonstrating that genes associated with “response to interferon-gamma” in the biological process category were enriched, demonstrating that enrichment of these gene sets is associated with TIL (tumor-infiltrating lymphocyte) activation in gene expression." (PMID 35058524, 2022). "In addition, the infiltrating results of myeloid-derived suppressor cells (MDSCs) and the M2 subtype of tumor-associated macrophages (TAM.M2) and the expression of interferon-γ (IFNG) were significantly different between the different risk subgroups and correlated with the risk score." (PMID 36172179, 2022). "The results indicated that Met at 10 μM, a physiologically relevant concentration, could enhance the IFNγ production by CD8+ T cells upon TCR stimulation and that Met at concentrations high enough to downregulate OCR of tumor cells, hampered the IFNγ production of CD8+ T cells." (PMID 35844589, 2022). "To determine the role of B7 family molecules and tryptophan degrading enzymes (IDO, TDO) in tumor and stromal cell interactions, we investigated the response of HepG2 cells and MSCs to cytokines commonly produced by infiltrating immune effector cells, such as IFNγ and TNFα." (PMID 34869307, 2021). "For example, adoptive transfer of a T cell type that induces a potent proinflammatory response, such as IL-17, may be beneficial from the perspective of tumour elimination, whereas IFNγ production in response to HBV antigens may be more advantageous in the context of viral control." (PMID 34377970, 2021). "Finally, DTCs dormancy may also depend on an equilibrium state with the immune surveillance system, exerted mainly by tumor-infiltrating lymphocytes (TILs) and NK cells and mainly regulated by the secretion of interferon gamma (IFNγ)." (PMID 33498251, 2021). "Intracellular acidification due to lactate accumulation disturbs nuclear factor of activated T cells (NFAT) production in NK cells, and this could explain the observed suppression of IFNγ expression and why neutralizing tumor acidity improves immunotherapy responses." (PMID 33670082, 2021). "However, tumor regression occurred in only a few mice (20% regression), and this increased antitumor effect was significantly diminished when the mice were treated with an IFNγ-neutralizing antibody." (PMID 33753998, 2021). "However, the more likely reason for the lower levels is that only a fraction (approximately 10%) of the added CAR T cells infiltrated the 3D tumor model, reducing the amount of T cells able to produce IFNG after encountering the tumor cells, compared to the situation in monolayer co-culture." (PMID 34267756, 2021). "Whilst significant expansion of tumor-specific T cells remained following vaccination with IFNβ in I/AEo/o mice, a greater than 3-fold decrease (5.5% vs 1.8%, p < 0.0005) was observed when compared to the percentage of IFNγ+ CD8+ T cells in wildtype C57BL/6 mice." (PMID 34552594, 2021). "Because anti-tumour T cell priming often occurs in the tumour-draining lymph node, we analysed T cells in the tumour-draining lymph nodes by IFNγ ELISpot to determine whether the modest increase in CD8+ T cells corresponded to an increase in tumour-specific T cell priming." (PMID 34784792, 2021). "We previously quantified the effect of CTLs on solid tumours, considering both cytotoxicity through direct cellular interactions and production of cytokines which inhibit tumour cell proliferation (e.g., IFNγ) as potential agents by which CTLs could control tumours." (PMID 34073822, 2021). "However, IFNγ is also a double-edged sword in the tumor microenvironment." (PMID 34136405, 2021). "Indeed, type-1 IFN release by pDC upon CpG binding may induce PD-L1 expression in both tumor and immune cells; additionally, T cells that are recruited to and are activated in the tumor microenvironment may induce PD-L1 expression through IFNγ release." (PMID 34359801, 2021).
tumor (continued). "In addition, T cells and interferon-gamma (IFN-γ) sensitize tumor cells to ferroptosis." (PMID 34977116, 2021). "Importantly, we observed increased IFNγ protein levels in tumours after indomethacin treatment." (PMID 34709754, 2021). "Moreover, high levels of IFNγ, produced also by activated NK cells, induced the expression of PD-L1 on tumor cells, which could sensitize PD-L1− tumor to PD-1-PD-L1 checkpoint inhibitor therapies." (PMID 33572396, 2021). "To verify whether the expression of TNFRSF9, TNF, and IFNG could identify all TILs actively engaged in tumor recognition in situ, we re-analyzed multiple scRNAseq datasets using fresh tumor biopsies and applied the activation gene sets as a proxy of presumed ongoing antigen stimulation in the TME." (PMID 34707600, 2021). "Moreover, we also found that an anti-IFNγ antibody effectively abrogated the tumor regression." (PMID 33753998, 2021). "Meanwhile, natural killer (NK) cells are a group of cells that could eliminate tumor cells and the release of cytokines, and NK cell-regulated production of interferon gamma (IFN-γ) is well known for its antiviral, immunoregulatory, as well as anti-tumor properties." (PMID 33732698, 2021). "Besides its role in creating a macrophage-dependent tumorigenic niche, IL-33 may directly promote TGFβ elicited Tregs differentiation, suppress IFNγ, and promote Tregs stability in the tumor." (PMID 33498483, 2021). "Besides exerting its effector activity, innate immune cells have a pivotal role in directing and shaping the type and strength of anti-tumour adaptive immune responses, through the release of pro-inflammatory signalling molecules such as interferon gamma (IFN-γ) and interleukin-12 (IL-12)." (PMID 34073106, 2021). "However, IFNγ also induced JAKs-STATs signaling pathways in tumor cells." (PMID 34685495, 2021). "Therefore, it can be speculated that the immunopeptidome of IFNγ exposed tumors confer a higher level of anti-tumor immunity due to the presence of IFNγ-dependent peptide antigens." (PMID 33968037, 2021). "Interestingly, the frequency of classical CD14+ HLA-DR+ monocytes prior to therapy was found to be a strong predictor of response, thought to reflect myeloid expansion triggered by IFNγ produced by activated tumor-specific and infiltrated T cells in patients who are more likely to become responders." (PMID 33842331, 2021). "Furthermore, T cells from tumor-draining LNs produced IFNγ and TNFα even during tumor progression." (PMID 33408092, 2021). "When monocytes are stimulated by inflammatory factors, such as interferon-gamma and lipopolysaccharide, they activate M1 macrophages, which can secrete inflammatory factors, such as IL-6 and tumor necrosis factor-alpha, and can phagocytize invasive pathogens and tumor cells." (PMID 33737938, 2021). "Hence, we tested whether the combined intracellular detection of CD137, TNF, and IFNγ was feasible, and whether the addition of CD107a to the panel enhanced the detection of tumor-specific reactive TILs in vitro." (PMID 34707600, 2021). "Yet, while NK cells may play a non-redundant role in controlling MHC-I-null and IFNγ-resistant tumor variants, a higher incidence of such tumors in patients with acquired immunotherapy resistance signifies an escape from NK cell-mediated control." (PMID 34201655, 2021). "In addition, the expression of VDAC2 and IFNG were decreased in the tumor tissues." (PMID 34885178, 2021). "Interestingly, tumors of mice vaccinated with Ad-mAFP-DC (6–10 days after tumor induction) already showed changes within the tumor into a shift towards a Th1 cytokine milieu, expressing significantly more IL-12, IFNγ, IL-2 and GM-CSF compared to mice vaccinated with Ad-LacZ-DC (p < 0.05)." (PMID 34282787, 2021).
tumor (continued). "Furthermore, blockade of IFNγ with a neutralizing antibody abrogated the ability of T cells to kill tumor cells, suggesting the role of T cell-derived IFNγ in the regulation of MHC molecules and therapeutic responses to αGITR + αPD1 potentially through direct recognition of antigens." (PMID 33976133, 2021). "Besides APCs, other immune cells, such as T cells, can also express IFNγ to suppress tumor growth." (PMID 33456564, 2021). "Of note, the simultaneous in situ detection of the corresponding genes, TNFRSF9, TNF, and IFNG, could represent a rapid and effective strategy for the identification and future functional characterization of the majority of the tumor-specific reactive TIL repertoire in scRNAseq data." (PMID 34707600, 2021). "Interestingly, when treatments with the β-AR agonist isoprenaline were administered daily to mimic chronic stress conditions, the capability of CD8+ T cells to directly kill tumour cells was impaired, along with their ability to produce interferon-gamma (IFN-γ)." (PMID 34295535, 2021). "Indeed, intratumoral NK-derived cytokines and chemokines promote DC recruitment and survival at the tumor site; moreover, NK cell-derived IFNγ efficiently promotes DC maturation (editing), which contributes to the development of a Th1-oriented response and amplifies the programming of CTL responses." (PMID 34065399, 2021). "Finally, to test whether stimulation of IL-18 receptors could induce IFNγ production by TILs, we added rhIL-18 to the media of TILs expanded in culture from tumor fragments for 20 days (n = 20)." (PMID 33430344, 2021). "Similarly, cytokine fusion compounds which deliver for instance TNFα or IFNγ to tumor vessels in PNET induce vessel normalization and/or vessel wall inflammation without TLS formation demonstrating the unique opportunities of targeting LIGHT into the tumor microenvironment." (PMID 34122434, 2021). "Both M0 and SFV/IFNg vector macrophages demonstrated inhibitory effects on the spheroid growth, so it was unclear whether vdIFNg-activated M1 macrophages can preferentially suppress tumor growth compared to M0 macrophages." (PMID 34835178, 2021). "It is markedly different from the evidence that IFNγ promotes vascular normalization, which might be because the IFNγ expressed in tumor cells produced a higher and more persistent systemic concentration than the transient IFNγ elevation that can be stimulated by ICB." (PMID 34476218, 2021). "The expression of PD-L1 on ICs appears to be of greater magnitude and of longer duration than on TCs and PD-L1 expression is IFNγ-dependent in TCs but only partially IFNγ-dependent in ICs, suggesting that the majority of PD-L1 in the immunosuppressive tumor microenvironment may be provided by ICs." (PMID 33804698, 2021). "Thus, IFNγ release by activated T cells induces PD-L1 up-regulation in tumor cells." (PMID 34447383, 2021). "Furthermore, F. nucleatum induced PD-L1 expression by activating STING signaling and increased the accumulation of interferon-gamma (IFN-γ)+ CD8+ tumor-infiltrating lymphocytes (TILs) during treatment with PD-L1 blockade, thereby augmenting tumor sensitivity to PD-L1 blockade." (PMID 34795206, 2021). "Despite earlier reports of IFNγ-mediated regulation of Gal-9 expression in human endothelial and mesenchymal stromal cells, we found that Gal-9 expression is primarily upregulated by IFNβ in tumor cells, whereas Gal-9 secretion is promoted by the combination of IFNβ and IFNγ." (PMID 33547304, 2021). "These may include therapies that directly supply T cell chemotactic chemokines, such as CXCL-9, -10, and -11, into tumor or promote their production from tumor cells, or deplete Tregs, or therapies that block IFNγ or its induced immunoregulatory effects through blockade of IDO or PD-1." (PMID 34943886, 2021).
tumor (continued). "Herein, we found that indomethacin enhances anti‐tumour immune responses, including increasing CD8+ T cell population and IFNγ secretion in a humanized mouse model, implying indomethacin plays a vital role in the tumour microenvironment and may be a potential anti‐immunosuppressive strategy." (PMID 34709754, 2021). "In addition, they open the possibility that long-term inhibition of interferon-gamma signaling may impair the elimination phase of immunoediting and, thus, promote tumor progression." (PMID 33623012, 2021). "We demonstrate for the first time in this study that this cluster is mostly characterized by aCasp1+ tumor cells and production of mature IL-18 associated with the highest level of Tbet+ and PD1+ TILs, possibly resulting in TIL exhaustion, in accordance with the lowest level of IFNγ." (PMID 33430344, 2021). "Finally, we asked whether the reduced frequency of IFNγ+CD44+CD8+ TILs in therapy-treated DIO mice was accompanied by increases in the frequencies of myeloid-lineage cells within tumor-bearing kidneys." (PMID 34064933, 2021). "We further introduced several published transcriptomic-based predictors as previous study, including the proliferation index, interferon-γ (IFNγ) signature score as well as cytolytic activity score, and performed a multivariate Cox regression analysis with age, tumor stage, and our classifier." (PMID 34745202, 2021). "Furthermore, since IFNγ secreted from NK cells plays an important role in tumor immunity and was found to be produced by NK cells in HSD-fed mice, we next investigated whether NK cell–driven IFNγ is critical in tumor immunity induced by HSD." (PMID 34516769, 2021). "We first assessed several human macrophage cell lines, which all responded to IFNγ by upregulating NAMPT expression, in parallel with the positive control IFNγ target CXCL10, leading us to investigate a role for this metabolic enzyme in regulating human tumor-associated immune responses." (PMID 33976173, 2021). "Treatment of CT26 syngeneic mouse tumors with the CDK4/6 inhibitor abemaciclib led to an increase in tumor-infiltrating T lymphocytes, and a significant upregulation of T-cell activity, as evidenced by the increased expression of T-lymphocyte activation markers (e.g., IFNG, GZMB, CCL4 and CCL5)." (PMID 33859752, 2021). "CpG methylation of IFNG gene could induce immunosuppression of tumor-infiltrating lymphocytes." (PMID 32296631, 2020). "The capacity of CSCs to increase kynurenine release and AhR activation to the NK cell release of IFNγ may be important to the initiation and development of immune suppression in the tumour microenvironment, especially as NK cells are often the first cytolytic cell to encounter tumours." (PMID 33375613, 2020). "However, when we further studied the function of tumor infiltrating lymphocytes, we found that intravenous iron supplementation significantly reduced the production of cytokines IL-2 and IFNγ by tumor CD8+ cytotoxic T cells, indicating iron-dependent reduced functionality of these cells." (PMID 33344239, 2020). "Additionally, recent studies have revealed that IFNγ, formerly acknowledged as a prototypical anti-tumor mediator, might play a multi-functional role in cancer development by displaying tumor-enhancing properties." (PMID 32069807, 2020). "Another interesting senescent-promoting process that tumor cells may utilize is the release of protein- and RNA-containing exosomes, which when taken up by T cells, cause loss of CD27/CD28 expression, proliferation and IFNγ production." (PMID 32570952, 2020). "Additionally, the tumor itself may influence effector cell function through the expression of signals such as PD-L1 in response to exposure of elevated IFNγ levels." (PMID 32499782, 2020).
tumor (continued). "Interestingly, both tumor cell lysis and IFNγ production are correlated with tumor volume (P < .05), suggesting that tumors unresponsive to therapy—represented by the bigger tumors in this cohort—contain exhausted T cells that reactivate upon removal from their immune suppressive milieu." (PMID 32642679, 2020). "Moreover, loss of function mutations in molecules involved in the IFNγ signaling pathway such as JAK1, JAK2, and β2-microglobulin have been identified to render tumor cells unresponsive to IFNγ signaling and mediate intrinsic or acquired resistance to PD-1-targeted therapy." (PMID 33193345, 2020). "In line, genetical or antibody-mediated depletion of CD8+ T-cells in PI3Kγ−/− mice caused a reduced tumor control but no alterations in proliferation or production of IFNγ or GzmB of PI3Kγ-deficient T-cells isolated from either naïve or tumor bearing mice have been observed ex vivo." (PMID 33552053, 2020). "In addition to their direct role in tumor surveillance, NK cells contribute to the formation of an efficient anti-tumor microenvironment through the early and rapid production of anti-tumor effector cytokines, such as IFNγ, which act in a paracrine manner on the other immune components of the TME." (PMID 32397392, 2020). "Upon activation, we observed altered transcription of KITLG, TGFB1, IFNG, SPP1, IL17A and PDCD1, whose associated functions and expression pattern marked and improved OS of BrC patients, supporting that MCs contribute with a tumor stroma with anti-tumoral functions in BrC." (PMID 32722549, 2020). "As in the tumor tissues, IFNγ, IL-10, IL-17A, and IL-4 were measured and similar to tumor tissues, in vitro culture of T cells were found to have significantly increased levels of IFNγ and IL-17A, with G-CSFR−/− CD4+ T cells, while IL-10 and IL-4 levels were decreased compared to WT." (PMID 33042110, 2020). "A subsequent study not only found that miR-155 expression within T cells was required to limit syngeneic tumor growth and promote IFNγ production by T cells but also revealed that immune checkpoint blockade could rescue microRNA-155-deficient induced immune escape." (PMID 32122338, 2020). "IFNγ, which is found at greater levels within the irradiated tumour than at secondary sites, can also mediated T-cell survival post RT, suggesting targeting multiple tumour sites could increase the efficacy of immune responses." (PMID 33148287, 2020). "Several different tumor types express PD-L1 either due to up-regulation after mutations in the PD-L1 gene (CD274) or as a result of adaptive up-regulation after stimulation with inflammatory cytokines (i.e., interferon-gamma (IFNγ)) present in the microenvironment." (PMID 32325898, 2020). "This in turn may enhance IFNG secretion and the anti-tumor actions that this molecule promotes." (PMID 32973967, 2020). "Considering that interferon gamma (IFN-γ) had been reported to induce PD-L1 expression in many tumor cells, we investigated whether it was also the case in stable TNBC cell lines with NPM1 silenced by lentiviral short-hairpin RNA (shRNA) and downregulated PD-L1." (PMID 32245950, 2020). "Additionally, multigene signatures comprised of IFNγ-inducible and other inflammatory genes meant to capture the complexities of the tumor microenvironment beyond PD-L1 protein expression were associated with response to checkpoint inhibitors in some tumor types." (PMID 33076423, 2020). "Similarly, effector Th1 responses, such as increased IFNγ production, concurrently lead to increased expression of PD-L1 on multiple cell types, including tumor cells and macrophages, which can engage the PD-1 receptor on T cells to suppress anti-tumor immunity." (PMID 33022920, 2020). "Moreover, PD-L1 expression was upregulated by cancer cells when the tumor was infiltrated with active T cells and in response to the production of interferon-gamma (IFNG); therefore, high PD-L1 expression might indicate a preexisting T-cell response." (PMID 33299118, 2020).